MTOR (mechanistic target of rapamycin kinase)
Diseases named in the same sentence as MTOR in open-access papers (continued):
Sharing a sentence is not in itself a finding about the gene and the disease.
glioma (continued). "ESM1 could also exert a pro-angiogenesis effect via PI3K/Akt/mTOR signaling in human gliomas." (PMID 36522312, 2022). "In addition, ESM1 was reported to promote cancer progression and invasion by regulating numerous pathways, including DLL4-Notch, NF-κB, PI3K-Akt-mTOR, and Wnt/β-catenin signalings in human adrenocortical carcinoma, colorectal cancer, breast cancer, glioma, and prostate cancer." (PMID 36522312, 2022). "Aberrantly expressed, circRNAs play an important role in glioma proliferation, cell cycle, invasion, and metastasis via regulating complementary miRNAs or targeting mRNA that are related to tumor-associated signaling pathways, such as PI3K/AKT/mTOR and the Wnt/β-catenin pathway." (PMID 36358938, 2022). "Furthermore, the combinatorial inhibition of PI3K-α and mTOR was well tolerated models of glioma." (PMID 36555334, 2022). "Previously, CLK1 could modulate the chemoresistance of glioma cells via glycolytic signaling mediated by AMPK/mTOR/HIF-1α as well as participating in modulating the splicing process of gastric cancer, serving as an underlying therapeutic target against this malignancy." (PMID 35832557, 2022). "Furthermore, cell autophagy in glioma involves the activation of PI3K/AKT/mTOR signaling network." (PMID 33663509, 2021). "Moreover, the correlation between CRNDE and PI3K/Akt/mTOR pathway was explored to identify the mechanism in regulating TMZ-resistance in glioma, which might provide a new therapeutic target for GBM treatment." (PMID 34454479, 2021). "We wondered whether CCND1 and RAP1B could affect the PI3K/AKT/mTOR signaling pathway in glioma." (PMID 33676540, 2021). "Collectively, these results indicate that BTK/mTOR inhibition improves tumor response and may serve as the basis for clinical trials testing acalabrutinib/rapamycin combination therapy for patients with high-grade gliomas." (PMID 34577576, 2021). "However, as RTK/PI3K/mTOR is one of the pivotal pathways regulating cell growth and survival in cancer biology, targeting still remains a strong rationale for developing strategies against gliomas." (PMID 34063168, 2021). "Similarly, the p-mTOR expression observed in normal brain tissues with a mean H-score of 80, moderate p-mTOR staining with a mean H-score of 107 was detected in high-grade glioma samples in almost all cases." (PMID 31187466, 2020). "It usually functioned as a ceRNA; for example, it could prevent miR-19a and miR-93 from interacting with their target mRNAs and elevate the expression levels of PTEN and PHLPP2 respectively, which inhibited PI3K/AKT/mTOR pathway and eventually suppressed the proliferation of glioma." (PMID 33029125, 2020). "Therefore, we believed that one of the reasons for ARG affecting glioma cell proliferation might be due to the AKT/mTOR-mediated autophagy." (PMID 33015162, 2020). "Inhibition of mTOR may be detected as dephosphorylation of its substrates p70S6K kinase and 4EBP1 (4E binding protein 1) and are correlated with the autophagic process in gliomas." (PMID 32093151, 2020). "Thus, we hypothesized that the mTOR signaling pathway might be involved in hypoxic peritumoral neuronal injury in glioma and then induce the proliferation of glioma cells." (PMID 33110474, 2020). "We hypothesized that JMJD2A may regulate the activation of mTOR in glioma cells." (PMID 32256210, 2020). "It has been reported that miRNA miR-128, miR-422a and miR-603 inhibit IGF-I expression in glioma cells as overexpression of these miRNAs suppresses cell proliferation, migration and invasion and enhances apoptotic death through the inhibition of the mTOR signaling pathway." (PMID 33604294, 2020). "Importantly, levels of alanine, 2HG, glutamate, glutamine and aspartate were significantly reduced in XL765-treated cells in both of our models, thus identifying potentially translational metabolic biomarkers of IDHmut glioma cell response to PI3K/mTOR inhibition." (PMID 31324855, 2019).
glioma (continued). "Consequently, our data indicate that targeting molecular alterations of the PI3K/AKT/mTOR pathway in H3K27M glioma might represent a promising therapeutic approach worth validating in clinical trials that have already been initiated." (PMID 31998633, 2019). "Therefore, we speculated that ROS activated JNK and used the regulators SP, MK and Ra to examine the function of JNK and the Akt/mTOR signaling pathways in triptolide-treated glioma cells." (PMID 31157167, 2019). "In addition, inhibition of mTOR could suppress glioma cells progression, and mTOR has an interaction with miR-224-5p." (PMID 31179240, 2019). "Therefore, we hypothesized that hsa_circ_0037251 might be involved in glioma progression by influencing the expression of mTOR in a miRNA-mediated manner." (PMID 31875034, 2019). "Remarkably, mTOR hyper-activation and autophagy suppression are both implicated in a crucial standpoint of GBM pathophysiology, that is, maintaining the oncogenic properties of malignant glioma by promoting the growth and maintenance of glioma stem-like cells (GSCs)." (PMID 31387280, 2019). "Analysing mTOR inhibitor sensitivity, other metabolism targeting treatments and their combinations could help to find potential agents and biomarkers for therapeutic development in glioma patients." (PMID 30574020, 2018). "In addition, the knockdown of mTOR and Bcl‐2 reduced the tolerance of glioma cells to TMZ." (PMID 28064447, 2017). "Moreover, it has been shown that the radioresistance of glioma cells can in part be attributed to the deregulation of the PI3K/mTOR pathway and that p110α isoform specific PI3K inhibitors increase the cytotoxic effects of radiation therapy in in vitro and in vivo GBM models." (PMID 28624789, 2017). "These disappointing results may be explained in part by pre-clinical and phase I data that have suggested potential loss of negative feedback regulation over Akt, derived from the use of mTOR inhibitors alone or combined with standard chemoradiotherapy in the treatment of high grade glioma." (PMID 27043632, 2016). "Thus, mTOR and it-regulated signalings are important oncotargets for glioma." (PMID 27532105, 2016). "Therefore, we analyzed mTOR activation in GSK321-treated glioma cells." (PMID 27532105, 2016). "Importantly, even though no PTEN mutations were observed in IDH1/2-mutated gliomas, the mTOR pathway is nonetheless frequently activated in these tumours." (PMID 27624942, 2016). "Thus, we propose that Tspan8 is in complex with rictor-mTOR, which might be important for mTORC2 integrity and activation in glioma cells." (PMID 25761241, 2015). "Interestingly, Tspan8 silencing did not affect mTORC1 assembly (mTOR-Raptor association) or activation (indicated by phosphorylation of S6K1) in glioma cells." (PMID 25761241, 2015). "Alterations in these metabolites may have considerable potential as non-invasive biomarkers for monitoring response to PI3K/mTOR inhibitors in early phase clinical trials in children with glioma, thereby helping to optimize dosing and treatment of this disease which has devastatingly poor prognosis." (PMID 25084455, 2014). "We reasoned that the granule cell pS6 IR in the presence of the glioma could have resulted from epileptic discharge, while mTOR activation in granule cells of HS patients in the chronic stage of TLE may be related to neuronal hypertrophy, a hallmark of this disease." (PMID 22761730, 2012). "Moreover, blocking mTOR signaling reduces glioma cell proliferation." (PMID 20576128, 2010). "For example, Yao and colleagues reported that in the glioma TME, miR-15a and miR-92a derived from M2 TAM-derived exosomes inhibited glioma cell migration and invasion by activating the PI3K/AKT/mTOR signaling pathway." (PMID 39889181, 2025). "Further investigation revealed that 37 restrains glioma cell growth, stimulates autophagy and apoptosis, and counters tumorigenesis by disrupting the PI3K/Akt/mTOR pathway." (PMID 40076568, 2025).
glioma (continued). "Our data show that Methylstat markedly decreases the mRNA expression levels of PDK1, AKT, and mTOR in glioma cells, contributing to the suppression of the entire AKT/mTOR signaling cascade." (PMID 41011214, 2025). "By activating the PI3K/AKT/mTOR pathway, SERPINB6 promotes EMT in glioma, demonstrating its great potential as a new target for glioma treatment." (PMID 40665565, 2025). "Collectively, these data strongly suggest that SERPINB6 drives the malignant behaviour of glioma cells primarily through the activation of the EMT process, mediated by the PI3K/AKT/mTOR pathway." (PMID 40665565, 2025). "In gliomas, hnRNPH1 promotes tumor progression by regulating the splicing of the pseudogene PRELID1P6, leading to the activation of the Akt/mTOR signaling pathway." (PMID 40507967, 2025). "Research has shown that Sch B can inhibit the migration and invasion of glioma cells by suppressing the expression of p-Akt, p-mTOR, and MMP-9 in the PI3K/Akt-mTOR-MMP-9 signaling pathway." (PMID 39995410, 2025). "The findings indicated that overexpression of RPA3 enhances the proliferation, migration, and invasion of glioma cells through the phosphorylation of PI3K, AKT, and mTOR, thereby activating the PI3K-AKT-mTOR signaling pathway." (PMID 40642071, 2025). "As recapitulated in this analysis, the radiosensitizers investigated in pre-clinical studies for gliomas include ATM, mTOR and PARPis." (PMID 40667051, 2025). "This review interrogates the impact of the gut microbiota on glioma, focusing on critical pathways such as NF-κB, MAPK, PI3K/Akt/mTOR, and Kynurenine/AhR that drive tumor proliferation, immune evasion, and therapy resistance." (PMID 40075568, 2025). "Glioma-released exosomal miR-3591-3p promotes macrophage to the M2 phenotype by targeting CBLB to activate the JAK2/PI3K/Akt/mTOR and STAT3, thereby promoting glioma progression." (PMID 40443670, 2025). "In glioma cells, apoptosis and autophagy are integrated into a stress-responsive regulatory network defined by oncogenic PI3K/Akt/mTOR, Ras/Raf/MEK/ERK, and PLCγ1/PKC signalling." (PMID 41511337, 2025). "For example, IDH1-mutant glioma cells were shown to release D-2-hydroxyglutarate (D2HG), which promotes lactate accumulation in peritumoral neurons via the mTOR pathway, thereby increasing neuronal hyperexcitability and seizure risk." (PMID 40718831, 2025). "Our study highlights that TREM1 modulates the TLR4/PI3K/AKT/mTOR signaling axis to regulate biological functions and the PMT process in glioma cells." (PMID 41394801, 2025). "Particularly noteworthy is the mechanism of SERPINB6 in promoting EMT in glioma, which is achieved through the activation of the PI3K/AKT/mTOR signalling pathway." (PMID 40665565, 2025). "It induces glioma cell proliferation by activating MAPKs (p38 MAPK, ERK1/2, and JNK), c-Myc, AP-1, and NF-κB and induces antiapoptotic effects via PI3K/Akt/mTOR in glioma cells." (PMID 39941886, 2025). "Parallel to PI3K/Akt/mTOR, the Ras/Raf/MEK/ERK cascade also drives proliferation and apoptosis resistance in glioma cells." (PMID 41511337, 2025). "It has been shown that in gliomas OCT4 expression is maintained by the transcription factors FOXO1 and FOXO3 and suppressed by PI3K/Akt/mTOR, and its level is significantly enhanced when PI3K is inhibited simultaneously with mTOR or MEK." (PMID 38392188, 2024). "In glioma model, pelargonidine has been reported to deploy its activities via inhibition of phosphorylation of Akt, PI3K and mToR, and downregulation of VEGF." (PMID 39407193, 2024). "In glioma cells, AF can also play a role in inducing ferroptosis by the AMPK/ mTOR/ p70S6K signaling pathway." (PMID 38583115, 2024). "Recent in-depth molecular profiling and studies of the genetic landscape of pediatric low-grade gliomas led to the discovery of the paramount role of frequent upregulation of RAS/MAPK and mTOR signaling in the tumorigenesis and progression of PLGGs." (PMID 39056798, 2024).
glioma (continued). "Of interest, human GBM and IDH (isocitrate dehydrogenase)-wildtype glioma samples, which are known to have a higher activity of mTOR (TCGA), tended to display (p = 0.059) reduced expression of DNMT3A in comparison with “lower-grade gliomas”." (PMID 38481314, 2024). "In glioma cell lines, the inhibition of the PI3/Akt/mTOR pathway, cellular DNA damage, increased ROS generation, alterations of and consequent reduction in the mitochondria within cells, and increased apoptosis were observed." (PMID 39597073, 2024). "The IGF-1/IGF-1R signaling can activate the PI3K/AKT/mTOR pathway signaling pathway, which is closely related to AKT1 and PIK3CD and plays a critical role in glioma progression, promoting cancer cell proliferation and inducing drug resistance." (PMID 38665430, 2024). "As a downstream effector of PI3K/Akt signaling, mTOR is a vital mediator of PI3K signaling that combines metabolic pathways and signal transduction in gliomas." (PMID 38355574, 2024). "We also delved into the influence of these drugs on the mTOR and AMPK pathways, aiming to uncover their implications for glioma cell metabolism, proliferation, and apoptosis." (PMID 39521788, 2024). "In the current study, the molecular mechanism investigation showed that CBX2 activates the AKT/mTOR signalling pathway by inhibiting the expression of PTEN and affects the carcinogenicity and chemoresistance of glioma cells." (PMID 39114365, 2024). "Overall, our study revealed that PDZK1 acts as a novel oncogene in glioma by binding to AKT1 and maintaining the activation of the AKT/mTOR signaling pathway." (PMID 38669103, 2024). "We also found in both IDH1 MT glioma cell lines and a murine glioma model that VPA inhibited the mTOR pathway, and downregulated FASN mRNA and protein expression." (PMID 39149696, 2024). "Scientists have found that H19 is a potential tumorigenic lncRNA in glioma and have validated its contribution to the autophagy of glioma cells through the PI3K/AKT/mTOR pathway." (PMID 38355574, 2024). "Prior investigations have elucidated CAMK1D’s role in promoting glioma cell proliferation, migration, and invasion through the activation of the PI3K/AKT/mTOR signaling pathway." (PMID 38720162, 2024). "Resveratrol, a non-flavonoid polyphenol compound, has been found to suppress glioma cell growth by modulating oncogenic microRNAs as well as the NF-κB and PI3K/AKT/mTOR pathways." (PMID 39737152, 2024). "Pseudogene PRELID1P6 activates Akt/mammalian (or mechanistic) target of rapamycin (mTOR) pathway by increasing HNRNPH1-mediated TRF2 splicing and promoting glioma development." (PMID 38405130, 2024). "We will delve into the current literature regarding the role of autophagy in glioma pathogenesis by exploring the major pathways of JAK2/STAT3 and PI3K/AKT/mTOR and summarizing the current therapeutic interventions and strategies for glioma treatment." (PMID 37998723, 2023). "In xenograft glioma models, PKI-587, a dual PI3K/mTOR inhibitor, has been demonstrated to reduce tumor development and AKT phosphorylation." (PMID 37834408, 2023). "GSEA also showed that signaling pathways (MAPK, PI3K, Focal_adhesion‐PI3K/AKT/mTOR and EGFR) were significantly enriched in gliomas with high MAPK4 expression." (PMID 36999945, 2023). "The tumorigenesis of glioma is regulated by the miRNA-383-5p direct target VEGFA and the downstream mTOR signaling pathway, which highlights the value of researching VEGFA as a therapeutic target for glioma." (PMID 37592783, 2023).
glioma (continued). "MAPK4 functions as a prognostic indicator in glioma and promotes the proliferation and migration of GBM cells through the AKT/mTOR pathway." (PMID 36999945, 2023). "Our work demonstrates that MAPK4 is overexpressed in glioma and that it promotes the proliferation and migration of glioma cells via the AKT/mTOR pathway." (PMID 36999945, 2023). "It has been reported that BRCA1-related proteins inhibit the proliferation and migration of glioma cells and the self-renewal of glioma stem cells through the TGF-β/PI3K/AKT/mTOR signaling pathways." (PMID 37759912, 2023). "In high-grade glioma cell lines, PODNL1 has been demonstrated to stimulate cell proliferation and migration via the regulation of the Akt-mTOR axis." (PMID 37504302, 2023). "The nanoparticles activated pro-apoptotic caspase-3, inhibited lactic acid secretion, and inhibited mTOR and PKM2 (a key glycolytic enzyme) pathways in glioma cells." (PMID 37273792, 2023). "Overexpression of HIC2 decreased the phosphorylation levels of mTOR, AKT and 70S6k in LN229 and U251 glioma cells." (PMID 36650953, 2023). "In vivo studies show that fucoxanthin inhibits PI3K/AKT/mTOR in BALB/C mice injected with U251 and glioma U87 cells." (PMID 38202644, 2023). "Signaling pathways, including the MAPK, PI3K, focal adhesion‐PI3K/AKT/mTOR, and EGFR pathways, were enriched in gliomas with high MAPK4 expression." (PMID 36999945, 2023). "It has also been reported that in most malignancies including glioma, the apoptotic pathway is usually inactivated by the activation of various pathways such as PI3K/AKT/mTOR, MAPK, Nuclear factor erythroid 2-related factor 2 (Nrf2) to maintain tumorigenesis." (PMID 37025487, 2023). "This drug induces, in glioma cells, both autophagic cell death via the inhibition of the PI3K/AKT/mTOR pathway and cycle arrest in the G2/M-phase by increasing the expression of the cyclin-dependent kinase (CDK) inhibitor P21." (PMID 36983018, 2023). "Signaling pathways such as the MAPK, PI3K, focal adhesion‐PI3K/AKT/mTOR, and EGFR pathways were enriched in gliomas with high MAPK4 expression." (PMID 36999945, 2023). "Temozolomide (TMZ) was shown to induce autophagy in the U251 glioma cell line, based on LC3-I to LC3-II conversion, as well as down-regulation of mTOR activity together with the mTOR downstream targets, S6K, and 4E-BP1." (PMID 36831202, 2023). "In addition, PI3K/mTOR or FOXO1 inhibitors could prevent glycolysis in gliomas." (PMID 37821870, 2023). "Celastrol suppressed glioma cell growth by increasing ROS production and dephosphorylating AKT and mTOR." (PMID 37351718, 2023). "Consistent with melanoma publications, most of the glioma studies postulated that the decrease activity of PTEN is related to tumor progression and that the activation of the mTOR pathway was able to override BRAFv600e-induced senescence." (PMID 36831610, 2023). "MAPK4 functions as a prognostic indicator in glioma and promotes the proliferation and migration of glioma cells via the AKT/mTOR pathway." (PMID 36999945, 2023). "Previous studies have reported that MTOR and WNT signaling play important roles in cellular growth, migration and survival in glioma progression 23-25." (PMID 37151881, 2023). "NSCs of the SEZ are considered glioma cells of origin, and molecular alterations of the EGFR/PI3K/AKT/mTOR module are hallmarks of this cancer type, which has led to the design of clinical trials devised to target this pathway." (PMID 37542079, 2023). "In summary, we found that CAMK1D promotes glioma cell proliferation, migration, and invasive processes through activation of the PI3K/AKT/mTOR signaling pathway." (PMID 35494053, 2022).